NES (nestin)
Diseases named in the same sentence as NES in open-access papers (continued):
Sharing a sentence is not in itself a finding about the gene and the disease.
melanoma (continued). "Treatment with the combination of BRAFi and MEKi upregulated nestin expression only in melanoma cells with acquired resistance to BRAFi but not to MEKi." (PMID 35999349, 2022). "Nestin (important in proliferation), endoglin (important in neovascularization), and VEGF-C (important in lymphangiogenesis) have already been described in cutaneous melanoma in general; but with little emphasis on thin melanomas." (PMID 36150976, 2022). "We describe the clinical data of thin melanomas patients with and without metastases and the immunohistochemical expression of nestin, endoglin, and VEGF-C." (PMID 36150976, 2022). "Although, unlike Nestin, there is no commonly accepted role of Fascin regarding melanoma malignancy." (PMID 35054386, 2022). "Melanoma harbors high cell heterogeneity including multi-subpopulations of cancer cells, some of which, due to their stemness features, are identified as melanoma stem cells and can be detected by the neural cell surface marker CD133, as well as by the neuroectodermal internal marker nestin." (PMID 33348804, 2020). "Other potential markers that could be used for the identification of melanoma CSCs are members of ABC family (ABCG2, ABCB5), CD166, and nestin." (PMID 33424978, 2020). "In addition, most GFP+ melanoma cells now expressed Nestin, GFAP and Tubb3, reminiscent of human melanomas known to frequently express these neuronal markers." (PMID 31685822, 2019). "Although GFP expression was also occasionally detected in the dermis, none of the GFP+ dermal cells expressed melanocyte and/or melanoma markers, including Sox10, S100b, and Nestin 32–34." (PMID 31685822, 2019). "Nestin, CD133, receptor activator of NF-k B (RANK), ATP-binding cassette sub-family B member 5 (ABCB5), CD20, and CD271 have been identified as potential candidates for the identification of melanoma-initiating cells." (PMID 31330795, 2019). "In contrast to the others, some studies demonstrated that NESTIN, as neural stem cell marker, is not up-regulated in this type of spheroid cells as potent melanoma stem cells." (PMID 27054115, 2016). "Previous studies have identified a SP in melanoma cell lines propagated in vitro and have provided arguments supporting a chemoresistant and CSC-like phenotype including tumorigenic potential and expression of NES or JARID1B." (PMID 24098529, 2013). "Comparison of immunoexpression of CD133, ABCB5, CD166 and Nestin in tissues with different primary lesion thicknesses revealed greater expression of CD133 and CD166 in primary melanomas that demonstrated >1.00 mm thickness compared to those that were less than ≤1.00 mm." (PMID 22922842, 2012). "It is worth noting that circulating Nestin and CD133 double-positive cancer cells have been detected in the peripheral blood of advanced melanoma patients, suggesting that both proteins may contribute to the malignant processes of melanoma." (PMID 38243233, 2024). "Previous studies demonstrated that nestin knock-out does not affect vimentin expression, which suggests that YB-1 plays some role in the upregulation of both nestin and vimentin, which are both highly relevant prognostic markers of malignancy in melanoma." (PMID 39086667, 2023). "Interestingly, in YB-1 melanoma knock-out cell line, nestin was nearly absent and vimentin was expressed at significantly lower levels." (PMID 39086667, 2023). "These melanoma cells lacked expression of neuronal markers Nestin, GFAP and Tubb3." (PMID 31685822, 2019). "In addition, herein increased expression of stem cells and metastasis related markers CD133, nestin, CXCR4, and NGF-R along with continued high-level of CD10 expression were observed, which usually delineates progression to advanced stage of melanoma and metastatic tumour formation." (PMID 28125999, 2017).
melanoma (continued). "The present case report clearly demonstrated that intermediate filaments, including cytokeratin, peripherin, α-internexin, GFAP and nestin, were not expressed in the signet-ring cell melanoma, although, peripherin and nestin are commonly expressed in malignant melanoma." (PMID 24348822, 2014). "Thus, a single marker may not be sufficient to isolate CSCs, and as a result, several markers are employed together to isolate certain types of CSCs, such as CD44+CD133+CD24+ cancer stem-like cells involved in murine melanoma, CD133+CD34+ melanoma CSCs, and CD133+/nestin+ lung cancer CSCs." (PMID 22558209, 2012).
Stroke (50 papers, 2012 to 2025). Sudden impairment of blood flow to a part of the brain due to occlusion or rupture of an artery to the brain. "The spatiotemporal distribution and morphology of PDGFR-β-positive cells in the lesion core were similar to those of nestin-positive cells, which were exclusively associated with vessels in the ischemic core of stroke-lesioned rats." (PMID 30455628, 2018). "Consistent with the neuroprotective role of NSCs, targeted depletion of both DCX- or Nestin-expressing cells in the SVZ has been linked to worsened stroke lesion size and motor impairment." (PMID 26696816, 2015). "An elevated expression of Nestin is also observed in reactive astrocytes and other glial cells following central nervous system injury, such as stroke or traumatic brain injury." (PMID 40747152, 2025). "In a photothrombotic stroke model, lineage tracing revealed that nestin-positive endogenous NSCs originating from the SVZ show increased proliferation in response to stroke, migrate toward the infarct region, and differentiate into astrocytes and neurons." (PMID 37335434, 2024). "In this study, to elucidate this, we transplanted h-MSCs into post-stroke nestin–GFP transgenic mice." (PMID 38891071, 2024). "Then, the same numbers of mCherry+ h-iSCs (5.0 × 104 cells/μL) or mCherry+ h-MSCs (5.0 × 104 cells/μL) were transplanted into the post-stroke mouse brains of nestin-GFP transgenic mice 6 weeks after MCAO." (PMID 39596134, 2024). "Nestin is a marker of proliferating pericytes and astrocytes that detach from damaged blood vessels after stroke." (PMID 34382128, 2022). "As detailed in Section 3.5, early reperfusion increased the number of nestin+ NSPCs at peri-ischemic areas at 7 d post stroke." (PMID 32492968, 2020). "Immunohistochemistry at 7 d post stroke confirmed that nestin+ cells were observed within and around ischemic areas after 90-min t-MCAO and p-MCAO." (PMID 32492968, 2020). "Nestin-positive cells were abundant in the post-stroke cortex as well as Musashi-1-positive cells (another NSPC marker), although to a lesser extent." (PMID 33132848, 2020). "One day post stroke, nestin+ cells were scarcely observed within and around the ischemic areas after 90-min t-MCAO and p-MCAO." (PMID 32492968, 2020). "Nestin is known to be re-expressed by astrocytes when they respond to a central nervous system (CNS) lesion from stroke, tumour growth, or neurodegenerative diseases and become activated." (PMID 31137614, 2019). "In our stroke model, by contrast, nestin+ cell-specific AHRcKO mice and TMF treatment inhibited AHR and reduced acute ischemic inflammation." (PMID 31606043, 2019). "In contrast, deletion of IL-1R1 in IL-1R1fl/fl Δ Nestin mice altered microglial process coverage of neurons, which indicates changes in microglia-neuron interactions after stroke." (PMID 30453020, 2019). "Experimental stroke in IL-1R1fl/fl Δ Nestin mice resulted in significantly smaller (25% reduction, p = 0.0379) brain injury compared to IL-1R1fl/fl mice that received identical tamoxifen treatment." (PMID 30453020, 2019). "Our previous study demonstrated that, in the ischemic core of stroke-lesioned rats, nestin expression is induced in a novel subset of vascular wall cells that are distinct from endothelial cells, pericytes, or smooth muscle cells." (PMID 30455628, 2018). "After day 7, the intensity of the nestin signal slowly decreased reaching the baseline value at 10 days and stayed at that level till 2 weeks following stroke." (PMID 28253906, 2017). "Taken together, quantitative analysis of the GFP, GFAP, and nestin-positive cells revealed a significant increase in cell numbers starting at 3 days and peaking 7 days after stroke." (PMID 28253906, 2017). "Namely, the quantitative analysis revealed a significant increase in the numbers of the GFP and nestin-positive cells at 7 days after initial stroke." (PMID 28253906, 2017).
Stroke (continued). "Next, proliferation of endogenous NSCs was detected using BrdU/Nestin immunofluorescence at 14 days after stroke." (PMID 27212231, 2016). "Eight days after stroke, abundant CD15+Nestin−, and in particular CD15+Nestin+ cells were found in the SVZ and RMS in pure stroke animals, but those CD15+Nestin− or CD15+Nestin+ cells had almost disappeared in stroke animals treated with Ara-C." (PMID 27589699, 2016). "Conditional deletion of shh in nestin-expressing cells resulted in more severe motor behavior deficits in shh iKO mice compared to their wt littermates at 7 days post stroke." (PMID 25927436, 2015). "The TAM treatment regimen utilized in this study likely resulted in the deletion of shh genes both in the SVZ nestin-expressing cells and its progeny as well as nestin-upregulated astrocytes near the stroke site." (PMID 25927436, 2015). "Using the same transgenic mouse line, a previous study in the young adult showed stroke induces nestin expressing neuronal progeny." (PMID 23118941, 2012). "Our data show that in response to stroke, nestin expressing cells in the SVZ of aged mice differentiated into neurons in the ischemic brain, although aged mice exhibit loss of nestin lineage neural stem cells in the SVZ." (PMID 23118941, 2012). "The present study shows that stroke induced nestin lineage neuronal and oligodendrocyte progeny and that Sildenafil significantly increased stroke-induced nestin lineage neuronal and oligodendrocyte progeny in middle-aged mice." (PMID 23118941, 2012). "Moreover, stroke-induced downregulation of downstream neurogenic markers (Cyclin D1 and Nestin) in the right hippocampus was ameliorated by BHD." (PMID 40973940, 2025). "By exploring the molecular mechanism of STAT3‐FOXO3 signaling axis, the novel cell‐free therapeutic product, EXO‐PD‐L1‐HGF‐activated endogenous nestin+ NPCs, might augment neurological functional recovery post‐stroke." (PMID 39049677, 2024). "Our data is in parallel with male studies suggesting the expression of nestin may contribute to formation of gliotic scar after stroke." (PMID 35413803, 2022). "PT stroke could also markedly elevate Nestin and Tuj1 positive area in both groups on days 6 and 22, with peak levels on day 6 after stroke." (PMID 35966576, 2022). "Previous studies also suggest that acupuncture enhances stroke recovery by targeting neurogenesis, with increased expression of neurogenesis markers: BrdU, Nestin (proliferation), PSAN-CAM (migration), and NeuN (differentiation), in experimental ischemic stroke animal models." (PMID 35368268, 2022). "However, 7 d post stroke, many nestin+ cells were observed within and around the ischemic areas after 90-min t-MCAO and p-MCAO." (PMID 32492968, 2020). "We further characterized the in vivo profile of surviving drNPCs (HuNu+ or STEM121+ cells) at 32 days post-stroke using immunostaining for Sox2 and Nestin (undifferentiated NPCs), GFAP (astrocytes), TUJ1 (immature neurons), NeuN (mature neurons), and Olig2 (oligodendrocytes)." (PMID 30747366, 2020). "In this study, the protein expression of IL-17 was downregulated by either giving As IV or knocking out IL-17, while the protein expression of Wnt2 and Nestin in the ipsilateral hippocampus was upregulated by knocking out IL-17 after stroke in vivo, by western blotting." (PMID 32317974, 2020). "In the stroke model, however, we cannot exclude that the subset of the nestin/Iba-1-positive cells may be of peripheral origin, thus representing the microglia/macrophage population." (PMID 28253906, 2017). "The expressions of Nestin and Bcl-2 proteins were remarkably up-regulated by PE after stroke." (PMID 29167635, 2017). "Although the origin of the nestin expressing microglia remains unclear, the increase in Iba-1/nestin-positive cells was more pronounced after stroke, where 7 days after injury, approx. 40% of activated microglial cells were nestin positive." (PMID 28253906, 2017).
Stroke (continued). "Additionally, aLA increased the relative mRNA expression of SOX2 and nestin when compared with the control group at 3 days after stroke (P < 0.05)." (PMID 25761600, 2015). "In summary, the present study demonstrates that Sildenafil enhances not only nestin lineage neurogenesis, but also oligodendrogenesis in the ischemic brain of the middle-aged mouse, which provides new insight into the therapeutic effect of Sildenafil on brain repair after stroke." (PMID 23118941, 2012). "The total number of proliferating NSCs (Nestin- and BrdU-positive cells) was markedly increased after TXC treatment within 7 days post-stroke." (PMID 34212980, 2021). "In this study, knocking out IL-17 significantly promoted the expression of BrdU, DCX, Nestin, and Sox2 in the SGZ after stroke in vivo, which was consistent with the results by giving As IV above." (PMID 32317974, 2020). "In the present study, to observe the neurogenesis in ischemic cortex after stroke regulated by IL-17 and As-IV, NPC markers-Nestin, GFAP and Sox2 and immature neuron marker-DCX, and mature neuron marker-NeuN protein expression was chose." (PMID 32818074, 2020). "Immunofluorescence staining revealed that a small amount of CD15+Nestin− and CD15+Nestin+ cells were located in the SVZ and the beginning of RMS before the establishment of stroke both in pure stroke and Ara-C-treated animals." (PMID 27589699, 2016). "To compare the induction and migration of DCX+ neuroblasts in a striatal stroke, we also carried out proximal MCAo in nestin-Cre ERT2/R26R-YFP animals and compared DCX staining to that in the cortical stroke brain." (PMID 25927436, 2015). "To examine the effect of Sildenafil on nestin-lineage oligodendrocytes in ischemic brain of middle-aged mice, we measured YFP+ and CNPase+ cells in middle-aged nestin-CreERT2/YFP mice after stroke." (PMID 23118941, 2012). "In the early phase of stroke, both HF-rTMS and iTBS increased the number of Ki67 and DCX/Nestin or NeuN+ cells suggesting that they could promote an increase in the neural stem cells (NSC) followed by a migration to the peri-infarct striatum." (PMID 36895285, 2023). "To ensure the specificlabeling of SVZ-derived NSCs but not reactive astrocytes, which also upregulatenestin after stroke, we treated the nestin creERT2-tdTomato mice with tamoxifen(TAM) for 5 days starting 22 days before stroke." (PMID 35905716, 2022). "In IF staining, protein levels of Nestin, Ki67, and DCX‐positive cells were significantly increased in the SGZ neurogenic niche of rats receiving three injections of CM compared with the untreated stroke rats (p < 0.05, p < 0.01, and p < 0.01, respectively)." (PMID 35715988, 2022). "Quantitative analysis showed that nestin+ areas within the ischemic and peri-ischemic areas were not significantly different between the models at 1 d post stroke, but were significantly larger at 7 d after 90-min t-MCAO compared to p-MCAO." (PMID 32492968, 2020). "Interestingly, we have found that, after stroke, aging not only decreases the number of astrocyte-like type B (in both sham and MCAO groups) but also of type-C cells (prominin-1+/EGFR+/nestin−/Mash1+ cells) in the SVZ, in this case, only after injury." (PMID 25958332, 2015). "By 14 days Nestin expressing reactive astrocytes are detected within the glial scar and possibly indicate a new cell population of reactive astrocytes that have migrated from the SVZ to the site of injury in response to stroke." (PMID 24809543, 2014). "A study in young adult nestin-CreERT2/YFP mice showed that stroke increases nestin lineage OPCs, but not mature oligodendrocytes." (PMID 23118941, 2012). "Nestin has also been described as absent from normal astrocytes and transiently expressed in reactive state, with a return to baseline levels at 7 days post-stroke, which is similar to our own findings with LPS intracerebral injection in the rat cortex." (PMID 40435721, 2025).
Stroke (continued). "EXO‐PD‐L1‐HGF facilitates endogenous nestin+ neural progenitor cell (NPC)‐induced neurogenesis via STAT3‐FOXO3 signaling cascade, which plays a pivotal role in cell survival and neuroprotection, thereby mitigating infarct size and enhancing neurological recovery in a murine stroke model." (PMID 39049677, 2024). "Previous evidence suggests that the nestin-positive progenitors may also give rise and differentiate into GFAP-positive astrocytes; we next investigated the cellular expression/induction patterns of nestin after stroke." (PMID 28253906, 2017). "Indeed, when stained with shh and nestin antibodies in post-stroke brain, we identified a number of cells in the SVZ in wt mice that are nestin+/shh+ (arrows) but only a few cells (arrow) in shh iKO animals to be shh positive, suggesting deletion of the shh gene in the SVZ niche." (PMID 25927436, 2015). "In addition, to examine the effect of local deletion of the shh gene in cortical nestin-upregulating cells after distal MCAo, it might be possible to inject tamoxifen into the cortical ischemic site after stroke to achieve restricted cortical but not SVZ nestin+ cell gene deletion." (PMID 25927436, 2015).